IGF1 (insulin like growth factor 1)
Diseases named in the same sentence as IGF1 in open-access papers (continued):
Sharing a sentence is not in itself a finding about the gene and the disease.
prostate carcinoma (continued). "In conclusion, our findings suggest that a high intake of phytoestrogens may lower the concentration of estradiol in patients with prostate cancer with a specific genetic upset of ERβ but does not affect serum concentrations of testosterone, IGF-1, and SHBG." (PMID 37049632, 2023). "Notably, IGF-1 expression was upregulated in prostate cancer of severe obese patients compared with non-obese patients." (PMID 36900168, 2023). "In addition, it was concluded that gut bacteria, functioning through short-chain fatty acids, regulated systemic and local insulin-like growth factor-1 (IGF1) in the host prostate, which may enhance the growth of prostate cancer cells in vivo." (PMID 35630763, 2022). "In our previous study, unfortunately, we could not show a correlation between serum IGF‐1 levels and prostate cancer incidence." (PMID 34606688, 2021). "While the mechanism by which MR inhibits prostate cancer development is not known, evidence suggests that MR may work by inhibiting prostate cancer cell proliferation, inhibiting the insulin/IGF-1 axis, or by reducing polyamine synthesis." (PMID 32138282, 2020). "Besides, GATA2 is a pioneer transcription factor for androgen receptor (AR) in prostate cancer, and increased GATA2 and its AR-independent transactivation of IGF2 could mediate taxane resistance through the activation of IGF1/insulin receptor signaling." (PMID 30935420, 2019). "IGF-1 induced PC3 cell proliferation, and the proliferation was increased by WT Flot-1 or KR mutant, but not CA mutant overexpression, suggesting that palmitoylation, but not sumoylation, of Flot-1 is responsible for IGF-1R signaling-mediated prostate cancer cell proliferation." (PMID 30631151, 2019). "Expression array showed that in prostate cancer cells VPA induces the up-regulation of TSP1 (Thrombospondin-1), multiple TIMP (Tissue inhibitor of metalloproteinase) isoforms and TGFβ (Transforming growth factor β), while expression of IGF1 (Insulin like growth factor 1) and VEGF is decreased." (PMID 28671573, 2017). "Furthermore, prostate cancer epithelial cells can stimulate their own growth by synthesizing and responding to IGF‐1 in an autocrine manner, as opposed to paracrine signaling." (PMID 27734632, 2016). "However, there is data that supports the idea that IGF-1 and IGF-1R could be used as biomarkers for advanced stages of prostate cancer and prostate cancer metastases." (PMID 24877145, 2014). "Contrary to what might be expected, serum IGF-1 levels were not the highest later in life during the progression to poorly differentiated (advanced) prostate cancer in the SV-40 Tag rats." (PMID 19171036, 2009). "In this randomized controlled dietary intervention study of patients with prostate cancer, an increased intake of phytoestrogens did not affect the serum of concentrations of testosterone, SHBG, and IGF-1." (PMID 37049632, 2023). "Patients with prostate cancer had higher serum IGF‐1 (143.8 vs 118.9 ng/mL) and PSA (8.6 vs 5.6 ng/mL) levels than men without prostate cancer (all P < 0.001)." (PMID 29992746, 2018). "Oxandrolone is currently the agent of choice, unless contraindicated with the presence of prostate cancer, as this agent is safe, easy to administer, and does not have the metabolic side effects of HGH, IGF-1, and insulin." (PMID 16921407, 2005). "Whilst androgens did not correlate with the MMPs, ADAMS, ADAMTS, or IGF-1/IGFBP-1 in these subjects with PCOS, androgens may modulate MMPs in other clinical conditions, such as prostate cancer." (PMID 39796177, 2025). "In advanced prostate cancer, the addition of xentuzumab to enzalutamide did not improve outcomes overall, although there was evidence of PFS prolongation in patients with high tumor IGF1 mRNA, albeit in a small sample." (PMID 31416218, 2019).
prostate carcinoma (continued). "Our results suggest that IGF-1, IGF-2, and IGFBP-3 measurements have no value in cancer screening, although IGF-1 and IGF-2 may be of aetiological significance in relation to colorectal and prostate cancer." (PMID 16804529, 2006).
Hyperglycemia (335 papers, 2003 to 2026). An increased concentration of glucose in the blood. "Hyperglycemia indirectly affects cancer cells by increasing circulating levels of insulin and insulin-like growth factor 1, which are associated with enhanced tumor cell proliferation and reduced apoptosis." (PMID 39812937, 2025). "Taken together, these findings imply that IGF-1 insufficiency contributes not only to hyperglycemia but also to dyslipidemia, compounding cardiovascular risk." (PMID 41393761, 2025). "Hyperglycemia itself causes dilation of the afferent arteriole through the release of vasoactive mediators such as insulin-like growth factor 1, glucagon, VEGF and prostaglandins." (PMID 39011442, 2024). "The underlying pathophysiological mechanisms of T2DM and CRC include hyperglycaemia, insulin-IGF-1 axis signalling, hyperinsulinaemia, inflammation caused by adipose tissue dysfunction, gastrointestinal motility disorders, and immune damage." (PMID 36890832, 2023). "The underlying mechanisms are manifold: besides hyperglycemia and elevated blood insulin levels with the stimulation of the IGF-1 pathway, several adipokines, secreted by the adipose tissue, promote carcinogenesis." (PMID 36547172, 2022). "The mouse model showed that only partial IGF-1 deficiency is responsible for reducing the liver expression of genes involved in glucose and lipid metabolism, leading to hyperglycemia and dyslipidemia." (PMID 34208601, 2021). "Hyperglycemia in preterm infants has also been associated with low insulin growth factor 1 (IGF1) levels." (PMID 33004691, 2020). "By P17, the streptozotocin-treated oxygen-induced retinopathy group had developed hyperglycemia associated with a significant decrease of plasma IGF1 levels." (PMID 33004691, 2020). "Hyperglycemia, insulin insensitivity, and low IGF1 levels in extremely preterm infants are associated with an increased risk of retinopathy of prematurity (ROP), but the interactions are incompletely understood." (PMID 33004691, 2020). "Hyperglycemia is associated with increased level Insulin-like growth factor 1 (IGF-1) and inflammatory cytokines, directly and indirectly influencing cancer cell proliferation, apoptosis, and metastasis." (PMID 32528752, 2020). "Mechanisms proposed to drive bone pathology in diabetic patients include deficiency in the secretion of insulin and insulin-like growth factor 1, impaired regulation of vitamin D and parathyroid hormone, and emergence of hyperglycemia." (PMID 29196931, 2018). "Another effect of hyperglycemia on bone turnover is dependent on deficiency of insulin and insulin-like growth factor-1 (IGF-1)." (PMID 27338453, 2016). "The mere partial IGF-1 deficiency is responsible for the reduction in the expression of genes involved in glucose and lipid metabolism, resulting in dyslipidemia and hyperglycemia." (PMID 26467524, 2015). "Other considerable risk factors for developing ROP are low IGF-1 levels, poor nutritional intake, hyperglycaemia, insulin treatment, corticosteroid treatment, insufficient intake of DHA and, of course, fluctuating/high oxygen concentrations." (PMID 24069180, 2013). "In conclusion, maternal hyperglycemia decreases DOL 21 male rat offspring hepatic IGF-1 mRNA variant levels and H3Me3K36 of the IGF-1 gene." (PMID 22548154, 2012). "In humans, maternal hyperglycemia often generates large for gestational age infants and increases IGF-1 serum levels at birth, yet it still predisposes to alterations in postnatal growth and to adult onset insulin resistance." (PMID 22548154, 2012). "Here we show that early deficits in insulin and C-peptide availability and decreased presence of IGF-1 as well as hyperglycemia are associated with impaired functions of unmyelinated and myelinated nerve fibers." (PMID 19834568, 2009).
Hyperglycemia (continued). "Moreover, obesity-linked insulin resistance and hyperglycemia increase unbound insulin growth factor-1 (IGF-1) protein in the blood, activating insulin and IGF-1 receptor signaling pathways that ultimately promote tumor growth." (PMID 39410536, 2024). "Hyperglycemia caused a decrease in interleukin 6 (Il-6) and an increase in tumor necrosis factor alpha (Tnf-α), Il-10, F4/80, tumor growth factor beta (Tgf-β), and insulin-like growth factor 1 (Igf-1)." (PMID 36722656, 2023). "Therefore, the reduction of serum IGF-1 or the deficiency of IGF-1 receptors on the surface of osteoblast led to bone fragility under hyperglycemia." (PMID 36297386, 2022). "The hyperglycemia phenotype of female igf1-deficient could be rescued with recombinant IGF1 protein through intraperitoneal injection." (PMID 35966057, 2022). "The next causal effect was via IGF1, which is involved in inflammation and hyperglycemia." (PMID 36140236, 2022). "Hyperglycemia may affect the risk of cancer and cancer-related death through the direct mitogenic effect of insulin and the production of IGF-1 (insulin-like growth factor 1)." (PMID 36263231, 2022). "At the same time, IGF1 protein could rescue the hyperglycemia phenotype in igf1-deficient zebrafish." (PMID 35966057, 2022). "Excess GH causes IR and hyperglycemia, whereas IGF-1 reduces blood glucose levels." (PMID 34208601, 2021). "Hyperglycemia, a hallmark of metabolic syndrome, is implicated in the dysregulation of growth factors and metabolic hormones like insulin and Insulin-like growth factor (IGF-1)." (PMID 33614663, 2021). "Hyperglycemia is a hallmark of metabolic syndrome and is associated with insulin resistance, aberrant glucose metabolism, chronic inflammation, and the production of other metabolic hormones such as IGF1, leptin, and adiponectin." (PMID 33224954, 2020). "Data in this paper show that the mere IGF-1 deficiency in adult mice is responsible for altering the hepatic expression of genes involved in glucose and lipid metabolism leading to hypertriglyceridemia, hypercholesterolemia and hyperglycemia." (PMID 26467524, 2015). "We hypothesized that maternal hyperglycemia in rats would increase offspring serum IGF-1 levels, hepatic IGF-1 mRNA variants, and epigenetic markers of IGF-1 associated with gene elongation." (PMID 22548154, 2012). "However, the factors such as hyperglycemia, insulin deficiency, reduced serum levels of insulin-like growth factor-1 (IGF-1) and osteocalcin, accumulation of advanced glycation end products (AGEs), especially in collagen, microangiopathy, and inflammation reduced bone quality in diabetic patients." (PMID 36297386, 2022). "However, hyperglycemia, insulin deficiency, reduced levels of insulin-like growth factor-1 (IGF-1) and osteocalcin in serum, accumulation of advanced glycation end products (AGEs) in collagen, microangiopathy, and inflammation, reduce bone quality in diabetic patients." (PMID 36297386, 2022). "Hyperglycemia may be a clinical presentation of low IGF-1 only instead of a real cause of ROP." (PMID 25766465, 2015). "We hypothesized that maternal hyperglycemia would increase IGF-1 mRNA variants and H3Me3K36." (PMID 22548154, 2012). "However maternal hyperglycemia decreased hepatic IGF-1 mRNA variants and H3Me3K36." (PMID 22548154, 2012). "Hyperglycemia in preterm infants can lead to low levels of insulin-like growth factor 1, which is a cytokine necessary for neovascularization formation in the retina." (PMID 40416432, 2025). "Hyperglycemia also augments insulin and insulin-like growth factor (IGF-1) signaling, activating the PI3K/AKT/mTOR pathway, which enhances cellular proliferation, survival, and angiogenesis while suppressing antitumor immune surveillance." (PMID 41479778, 2025). "The biological relationship between T2D and GBC likely involves hyperinsulinaemia, hyperglycaemia, and elevated concentrations of insulin-like growth factor 1 (IGF-1)." (PMID 41008833, 2025).
Hyperglycemia (continued). "In contrast, our geriatric, leaner Indian cohort likely exhibits impaired insulin secretion (low HOMA-B), limiting hepatic IGF-1 production despite hyperglycemia." (PMID 41393761, 2025). "Chronic hyperglycemia and inflammation alter liver function, reducing insulin-like growth factor 1 (IGF-I) and increasing IGFBP3 levels." (PMID 39682729, 2024). "DM is also known to contribute to hepatocarcinogenesis, and IGF-1 plays a pivotal role in hyperglycemia-induced hepatocarcinogenesis." (PMID 39123380, 2024). "Beyond the oversight of serum IGF1 concentrations, these visits serve to track potential adverse effects, such as fluid retention, hyperglycemia, arthralgias, and paresthesia." (PMID 39415786, 2024). "After 24 weeks of follow-up, IGF-1 levels were reduced to the reference range in 73.8% of patients, but the frequency of DM increased from 32.8% at baseline to 68.9%, explaining hyperglycemia as the most frequent adverse event." (PMID 39119396, 2024). "Hyperglycemia promotes the advancement of lung cancer through high levels of insulin receptor expression, and the IGF-1/IGF-1R pathway is known to play an essential role in the pathogenesis of lung cancer." (PMID 38468345, 2024). "The incidence of hyperglycemia indirectly influences tumor cells by inducing the production of insulin-like growth factor-1 (IGF-1) and inflammatory cytokines in circulation." (PMID 39410536, 2024). "In the early stages of DN, hyperglycemia causes the release of vasoactive mediators such as VEGF, NO, glucagon, insulin-like growth factor 1 (IGF-1), and prostaglandins." (PMID 37239172, 2023). "Hyperglycemia induces oxidative stress both directly and indirectly in BC cells in part by increasing levels of insulin/IGF-1 as well as inflammatory cytokines." (PMID 36849958, 2023). "IGF-1 is a direct target of miR-142-5p and/or miR-18b, and the downregulation of these two microRNAs in the retinal tissues of DR rats and human RCVECs stimulated with hyperglycemia leads to VEGF activation by affecting the IGF-1 and AKT signaling pathways." (PMID 37978169, 2023). "Further decrease in IGF-1 observed in diabetic rats treated with TDF compared with DC rats indicated that TDF exacerbated hyperglycemia in diabetic rats by reducing the IGF-1 level." (PMID 35122679, 2022). "Insulin also stimulates mitochondrial protein synthesis, and IGF-1 prevents hyperglycemia-induced oxidative stress, and the insulin/IGF-1 signaling defects make neurons more vulnerable to reactive oxygen species." (PMID 36361741, 2022). "Hyperglycemia impairs the response of osteoblast-like cells to insulin-like growth factor-I (IGF-1), potentially delaying bone formation." (PMID 36479259, 2022). "IGF-1 inhibited hyperglycemia-induced ROS production and prevented hyperglycemia-induced apoptosis by activating Akt/PKB in MCs." (PMID 35409370, 2022). "In animal studies, impaired dendritic development is described in offspring born to rats with streptozotocin-induced hyperglycemia in pregnancy—possibly through abnormal insulin/insulin-like growth factor 1 (IGF1) signaling in the fetal brain." (PMID 35472047, 2022). "There was a marked reduction in the level of pFOXO1Ser256 in cells incubated with IGF-1 in hyperglycaemia (30 mM glucose)." (PMID 34381074, 2021). "TXNIP expression remains elevated as long as hyperglycemia persists, while insulin and insulin-like growth factor 1 (IGF-1) reduce TXNIP expression, however, it lasts for a few hours only if hyperglycemia persists." (PMID 34940029, 2021). "Apart from directly promotes cancer progression, hyperglycemia increases the levels of insulin/IGF-1 and inflammatory cytokines in circulation." (PMID 34527591, 2021).
Hyperglycemia (continued). "In mouse OIR model combined with the HAR model, decreased liver IGF-1 expression is observed before the induction of hyperglycemia; IGF-1 treatment reduces retinal neovascularization and improves retinal revascularization." (PMID 34832995, 2021). "Hyperglycaemia inhibits the secretion of growth hormones, which eventually decreases IGF-1, leading to decreased osteoblast proliferation, collagen synthesis, and bone matrix formation, all of which further result in decreased bone quality." (PMID 34690653, 2021). "This is consistent with our findings of reduced Akt phosphorylation in HUVEC incubated under hyperglycaemia, both under basal conditions and in the presence of IGF-1, and corresponding changes in FOXO1 phosphorylation/activity in these cells." (PMID 34381074, 2021). "In premature infants with postnatal hyperglycemia in the first month, there are also lower plasma IGF-1 levels." (PMID 34832995, 2021). "The level of activity (pAktSer473) was found to be decreased by hyperglycaemia under both basal conditions and following IGF-1 stimulation in comparison with cells in normoglycaemia." (PMID 34381074, 2021). "Studies have shown the ability of NTS to enhance growth hormone signaling via the JAK2/STAT5b/IGF-1 axis and to produce anti-inflammatory effects against hyperglycemia in human monocytes." (PMID 34068523, 2021). "Hyperglycemia-induced suppression of IGF-binding protein synthesis and the promotion of IGF-1 synthesis increase the amounts of bioavailable IGF-1 in circulation; an established critical risk factor for several malignancies." (PMID 33614663, 2021). "Hyperglycaemia stimulated PlGF secretion in cultured primary endothelial cells, which was suppressed by IGF-1-mediated PI3K/Akt activation." (PMID 34381074, 2021). "Other factors such as insulin-like growth factor (IGF1), neuropeptide Y, and hyperglycemia inhibit GH secretion, and hypoglycemia, thyroxine, ghrelin, klotho, and glucocorticoids stimulate GH secretion." (PMID 34943879, 2021). "We discuss the use of antidiabetic drugs in a wide range of cancer therapy and cancer therapeutics in the development of hyperglycemia, especially antineoplastic drugs which often induce hyperglycemia by targeting insulin/IGF-1 signaling." (PMID 32498358, 2020). "In oxygen-induced retinopathy, hyperglycemia/hypoinsulinemia decreased liver IGF1 expression (P < 0.0001); rh-IGF1 treatment improved normal vascular regrowth (P = 0.027) and reduced neovascularization (P < 0.0001)." (PMID 33004691, 2020). "The data further support the use of IGF1 supplementation as a potential treatment to prevent ROP, especially in very preterm infants with hyperglycemia in the first week, when IGF1 levels are further compromised." (PMID 33004691, 2020). "In the Q141K+/+ mice, we observed significant hyperglycemia, significant increases in serum insulin, and IGF1, as well as increased fractional excretion of sodium." (PMID 32488095, 2020). "Mice with oxygen-induced retinopathy alone versus oxygen-induced retinopathy plus streptozotocin-induced hyperglycemia/hypoinsulinemia were assessed for glucose, insulin, IGF1, IGFBP1, and IGFBP3 in blood and liver." (PMID 33004691, 2020). "This is in agreement with previous studies that have shown several risk factors of ROP to be related to glucose metabolism: caloric intake, hyperglycemia, weight gain, insulin therapy, and as a consequence, IGF-1 levels." (PMID 30954975, 2019). "By 6weeks, prior to development of either hyperglycemia or albuminuria, fa/fa rats were hyperinsulinemic with high urinary IGF1/2 excretion, gaining weight rapidly, and had 1.6-fold greater glomerular volume than controls (P < 0.01)." (PMID 31811176, 2019). "Recently, postnatal weight gain, insulin-like growth factor 1 (IGF-1), hyperglycemia, maternal age, and genetic predisposition have also been implicated, as well as vitamin E and light exposure." (PMID 29181441, 2017).